POLD1 (DNA polymerase delta 1, catalytic subunit)
Diseases named in the same sentence as POLD1 in open-access papers (continued):
Sharing a sentence is not in itself a finding about the gene and the disease.
cancer (continued). "The median age at first cancer diagnosis was 40 years (range: 27–64 years) in 30 CRC patients carrying the POLE mutation and 32.5 years (range 23–57 years) in 13 CRC patients with POLD1 mutations." (PMID 27573199, 2017). "Since this seminal discovery, several publications have found evidence supporting roles for additional germline POLD1 and POLE mutations in cancer predisposition, in which carriers typically develop multiple adenomas, polyposis, CRC, and/or EC." (PMID 28117753, 2017). "Evidently, the identification of germline and somatic POLE and POLD1 mutations that cause CRC and EC is only the first stage in understanding how those changes act and, if possible, exploiting them for cancer prevention and therapy." (PMID 23447401, 2013). "By decoding POLD1’s intricate roles, we pave the way for tailored therapies that could transform outcomes in cancers long resistant to immunotherapy, heralding a new era in precision oncology." (PMID 40661943, 2025). "Although POLD1 and POLE have recently been suggested as genes predisposing to hereditary EC, absolute risk for EC and even other cancer types is very uncertain, therefore the POLD1/POLE genetic testing of unselected EC patients should be restricted to the research setting." (PMID 40936703, 2025). "The diverse expression profiles of POLD1 (DNA polymerase delta 1 catalytic subunit gene) in various tumor types indicate its potential significance across different cancers as reported in previous studies, even though its specific role in PCa remains less defined." (PMID 40626556, 2025). "Inhibitors of ATR or CHK1, such as berzosertib or prexasertib, could selectively kill POLD1-mutant tumor cells by exacerbating replication collapse, a strategy already showing promise in POLE-mutated cancers." (PMID 40661943, 2025). "Notably, POLD1-mutant tumors are predominantly MSS across most cancer types, yet exhibit significant tissue-specific variation." (PMID 40661943, 2025). "Moreover, the French Genetic and Cancer Group-Unicancer recommended including not only POLE but also POLD1 in multi-gene panel genetic tests to evaluate the predisposition to hereditary cancer of the digestive tract." (PMID 39001389, 2024). "This suggests that the mechanism of mutation acquisition is similar throughout the cancer history irrespective of the POLE/POLD1 mutation." (PMID 39233831, 2024). "Mutations in the POLD1 and POLD3 genes increase the risk of CRC and other malignant tumors." (PMID 39458936, 2024). "Although variants in POLM have not been directly associated with cancer risk, it is a putative predisposition gene since variants in other DNA polymerase genes (POLD1 and POLE) have already been related to CRC risk." (PMID 39408606, 2024). "With this review, we aim to summarize the current knowledge on the role of POLD1 in cancers." (PMID 36980791, 2023). "Additionally, in both mesothelioma, a rare and deadly cancer, and esophageal squamous cell carcinoma, POLD1 has been found to play a significant role in resistance to platinum-based chemotherapy." (PMID 36980791, 2023). "Meanwhile, POLD1 upregulation contributes to cancer cell proliferation, migration, and invasion, which may be attributed to surviving replication stress via improving their tolerance to DNA damage." (PMID 37047824, 2023). "Nevertheless, an attempt to organize the current knowledge and deepen understanding of POLD1 biology in carcinogenesis would be of paramount importance and could pave the way for novel anti-cancer drugs." (PMID 36980791, 2023). "Advancing our understanding of the POLD1 expression patterns in various cancer types in relation to meaningful clinical and pathological parameters may facilitate the translation of research knowledge into clinical practice." (PMID 36980791, 2023).
cancer (continued). "However, little is known about the influence of POLD1 expression level on the efficacy of ICI in cancer treatment." (PMID 36980791, 2023). "Unlike in POLE, where the overwhelming majority of cancer mutations are located in the exonuclease domain, POLD1 mutations occur in the exonuclease and polymerase domains, which is the location of the most recurrent POLD1 mutation, R689W." (PMID 37388540, 2023). "Candidate variants in the ExoD of POLE and POLD1 predispose to cancer and exhibit a strong mutagenic effect, however, the role of non-ExoD variants in mutagenesis and cancer risk has been controversial." (PMID 37095444, 2023). "All these findings have demonstrated the possibility of POLD1 as a biomarker for human cancers, and maybe a novel target in treating a variety of malignancies." (PMID 37047824, 2023). "Moreover, POLD1 upregulation contributes to cancer cell proliferation, migration, and invasion, as well as survival under replication stress via improving their tolerance to DNA damage." (PMID 35189839, 2022). "We determined the relationship between TMB or MSI and POLD1 mRNA expression in pan-cancer." (PMID 35189839, 2022). "The analysis revealed different implications of POLD1 deregulation in different cancer types." (PMID 35620275, 2022). "Patients with luminal cancers and a high TMB displayed a higher prevalence of mutations in MSI-related genes and genes encoding for the proofreading polymerases epsilon, POLE and delta, POLD1 compared with the group with low TMB." (PMID 35329928, 2022). "Moreover, ~12,000 tumor samples from TCGA database were collected, and the effect of POLD1 expression on prognosis was verified in pan-cancers." (PMID 34868924, 2021). "The role of POLD1 in the infiltration of immune cells in the tumor microenvironment was demonstrated, which may guide cancer treatment and targeted drug development." (PMID 34868924, 2021). "In addition, H2AFX, MCM2, MCM7, and POLD1 were highly up-regulated in 31 cancer tissues, based on the analysis of TCGA data." (PMID 33442399, 2021). "However, in some cancers, defective proofreading due to acquired POLE/POLD1 exonuclease domain mutations causes markedly elevated somatic mutation burdens with distinctive mutational signatures." (PMID 34594041, 2021). "Regarding those genes involved in germline predisposition to other cancers, ATM, APC, POLD1 or SDHC could be promising candidate genes for germline GC predisposition." (PMID 33525650, 2021). "When adjusting for cancer types and MSI status for multivariate Cox regression analysis, POLE/POLD1 mutations were found to be independent risk factors for identifying patients that could benefit from ICI treatment." (PMID 34026601, 2021). "Furthermore, POLE and POLD1 defects have been reported to be instrumental in the development of cancer, characterized by increased levels of transversions (G:C→T:A and A:T→C:G) and transitions (G:C→A:T)." (PMID 33339161, 2020). "Further analysis showed that POLE damaging variants may affect the cancer development through MMR, TGFβ and RTK/RAS/RAF signaling pathways, and POLD1 through MMR pathways." (PMID 31673068, 2019). "First, we noted that POLE/POLD1 exonuclease domain mutations were frequently clonal (13/15 POLE and 8/10 POLD1 mutations had an estimated cancer cell fraction [CCF] > 0.9) and that non-clonal POLE/POLD1 mutations appeared to be non-functional passenger events." (PMID 29717118, 2018). "Polymorphisms and mutations in POLD1 and POLD3 were reported to be associated with cancer risk." (PMID 28924235, 2017). "Additionally, the number of POLD1 and POLE mutations in human cancers will likely increase substantially as more cancer genomes are sequenced." (PMID 28117753, 2017).
cancer (continued). "By elucidating POLD1’s multifaceted contributions—from replication stress to immune evasion—we aim to illuminate its potential as a predictive biomarker and therapeutic target, paving the way for tailored strategies that exploit its vulnerabilities in the fight against cancer." (PMID 40661943, 2025). "These divergent phenotypes underscore the dual nature of POLD1 in cancer biology: while its overexpression may drive replication-associated mutagenesis in aggressive tumors, it can paradoxically act as a stabilizing force in malignancies where replication demands are less acute." (PMID 40661943, 2025). "PD-1 immunotherapy can achieved desirable response in cancer patients with sensitive gene mutations, including COL3A1, FGFR, breast cancer susceptibility (BRCA), ataxia telangiectasia-mutated gene (ATM), polymerase epsilon (POLE), DNA polymerase delta 1 (POLD1), NOTCH, KMT2C genes and so on." (PMID 39530091, 2024). "It is hypothesized that there are no cancers with an exclusive heterozygous POLD1 mutation and only a complete loss of the two POLD1 alleles can lead to cancer." (PMID 36980791, 2023). "This unanticipated data demonstrating the positive correlation of POLD1 nuclear immunoreactivity with longer overall survival among ccRCC patients, in contrast to several reports regarding other malignancies, may suggest that the potential role of POLD1 can be considered as cancer specific." (PMID 36980791, 2023). "One possible partial explanation for the relative lack of POLD1 mutations in cancer may be the role for Pol δ in what has been called ‘proofreading in trans’ or ‘extrinsic proofreading’." (PMID 37388540, 2023). "CRC and EC cancer patients with somatic POLE ED mutations have been shown to have a favourable prognosis and it would be interesting in future studies to investigate whether the prognosis of cancer patients with germline POLE or POLD1 mutations is also better." (PMID 33948826, 2022). "Besides, H2AFX, MCM2, MCM7, and POLD1 were highly up-regulated in 31 cancer tissues." (PMID 33442399, 2021). "Additionally, the role of POLD1 within RSV-mediated apoptosis of cancer cells is also unclear." (PMID 33747905, 2021). "In the mice model, when the exonuclease domain of Pol δ (encoded by the POLD1 gene) or Pol ɛ (encoded by the POLE gene) was inactivated by mutation at exonuclease, catalytic residue elevated base substitution mutation rates, and increased incidence of cancers was observed." (PMID 29500597, 2018). "Importantly, identifying POLD1 carriers also has direct therapeutic implications: the proofreading defect underlying PPAP may confer enhanced responsiveness to immunotherapy, representing a major opportunity in cancer treatment." (PMID 41487566, 2025). "Kaplan-Meier curves and log-rank tests were performed to show the effect of POLD1 expression on the OS and DFI of patients with various cancer types." (PMID 35189839, 2022). "Taken together, these cases constitute four patients with a digenic inheritance of a POLE/POLD1 PV and an MMR gene PV and an exceptionally young age of cancer onset." (PMID 36291559, 2022). "From our network, we observed that E2F1 regulates POLD1, ASF1B, FOXM1 and RACGAP1 which are up-regulated in all 15 cancer types (Subnetwork)." (PMID 30809433, 2019). "Since arriving on the market in 2011, the Ion Torrent PGM, a benchtop sequencer, has already been successfully used for the targeted resequencing of cancer genes, such as BRCA, BRAF, POLE and POLD1." (PMID 24705691, 2014).
cancer (continued). "Each case carried VUS in genes related to DNA repair (POLD1, BARD1, or BRIP1); however, given the uncertain classification of these variants, no direct inference regarding hereditary cancer predisposition can be made." (PMID 41595443, 2025). "Meanwhile, POLD1 may be a potential prognostic marker and promising therapeutic target in HCC and various cancers." (PMID 35189839, 2022). "Significant differential expression of POLD1 was commonly observed between cancer tissues and adjacent normal tissues in pan-cancers, such as GMB and STAD, and the expression of POLD1 was significantly higher in the HCC tumor group compared with the normal group." (PMID 34868924, 2021). "Deletions in the FANCA, POLD1, and STK11 genes were observed in cancer patients only." (PMID 33431054, 2021). "Except for increased cancer risk, individuals with germline POLE/POLD1 mutations do not exhibit overt features of premature aging." (PMID 34594041, 2021). "Since next generation sequencing technology offers significant benefits compared to single gene testing by reducing costs, time and increasing the sensitivity, it is feasible to screen multiple cancer related genes in EC patients using multigene panels including POLE and POLD1." (PMID 31866764, 2019). "However, it is still feasible to screen multiple cancer related genes in EC patients from Middle Eastern region using multigene panels including POLE and POLD1." (PMID 31866764, 2019). "Existing evidence have shown that TMB was higher in cancer patients with POLE and POLD1 variants." (PMID 31673068, 2019). "Although this is commonly seen in non-smoking associated cancers, we wish to stress the close link between transitions (mainly C-to-T) and MSI as well as POLE/POLD1 mutations in men." (PMID 31581674, 2019). "PPAP is a fairly recently described cancer susceptibility syndrome and guidelines regarding management of POLE and POLD1 mutation carriers do not yet exist." (PMID 25860647, 2015). "In this cancer sample, neither LOH, cnLOH, nor any somatic mutation affecting POLD1 (or any POLD1 subregion) could be identified in the second POLD1 allele." (PMID 38658779, 2024). "To compare the transcriptional expression of the POLD1 gene between tumor and non-tumor tissues, we first evaluated POLD1 expression in TCGA pan-cancer according to the TIMER online platform, and found higher POLD1 expression in various human tumors compared with their counterpart normal tissues." (PMID 37047824, 2023). "Hence, digenic inheritance should be considered and systematically analyzed in all childhood/AYA cancer patients in whom an identified heterozygous germline MMR gene or POLE/POLD1 PV does not alone explain the age of tumor onset and/or phenotype." (PMID 36291559, 2022). "However, the role of the top three genes (MMAA, SUCLG2 and CBR4) negatively correlated with POLD1 expression in cancers is not elucidated." (PMID 35189839, 2022). "Similarly, the genes for proofreading polymerases POLE and POLD1 are mutated in 7.5% and 4.5% of PIK3CA mutated cancers versus 2.2% and 0.6% of PIK3CA non-mutated cancers." (PMID 33435133, 2021). "We next aimed to determine whether POLE/POLD1- and MSI-mediated mutagenesis occurred simultaneously in the same cancer cells, or whether the events were separated spatially (i.e., occurring in distinct subclones) or temporally (i.e., defective in non-overlapping time intervals)." (PMID 29717118, 2018). "Therefore, molecular screening for POLD1 may be necessary for patients with such a cancer spectrum, regardless of their family history." (PMID 37746257, 2023). "In addition, POLD1 knockdown in ccRCC cells significantly decreased the levels of autophagy and ferroptosis signaling pathway-related genes, including p62, NRF2, Keap1 and GPX4, which were reported to serve as the vital regulatory factors in many types of cancers." (PMID 37047824, 2023).
cancer (continued). "Previous studies investigating the mechanism of the transcriptional regulation of POLE expression and mutations in carcinogenesis show that POLE or POLD1 mutations serve as negative prognostic markers and may predict a survival benefit from ICI therapy across diverse cancers." (PMID 34950188, 2021).
tumor (136 papers, 2009 to 2026). "The interplay between POLD1 mutations and immune evasion represents a critical aspect of tumor biology with significant implications for therapeutic strategies." (PMID 40661943, 2025). "The tumor phenotype linked to POLD1 often includes a high tumor mutational burden (TMB), POLD1-specific mutational signatures (SBS10d and SBS10c), and a microsatellite stable (MSS) and/or proficient mismatch repair (pMMR) status." (PMID 41487566, 2025). "Specific POLD1 mutations, such as somatic p.S478N and germline p.L474P, impair Pol δ proofreading, leading to ultramutated tumors with tumor mutation frequent loads exceeding 100 variants/Mb and characteristic SBS10d signatures." (PMID 40661943, 2025). "This dichotomy underscores a critical challenge: POLD1’s therapeutic relevance is highly context-dependent, influenced by tumor biology, mutation type, and coexisting alterations." (PMID 40661943, 2025). "Reflecting these insights, ESMO and NCCN guidelines now recommend testing for POLE/POLD1 mutations in MSS CRC with high tumor mutational burden particularly in right-sided tumors." (PMID 40805233, 2025). "PBRM1 loss sensitizes tumor cells to interferon-γ-mediated killing, complementing the neoantigen-driven immunogenicity of POLD1 mutations." (PMID 40661943, 2025). "A two-year-old patient with a history of neurofibromatosis type 1 (NF1), NF1 microdeletion and variants of uncertain significance in the CASR, NF2, and POLD1 genes, presented with intestinal subocclusion caused by a 15 cm heterogeneous pelvic tumor." (PMID 40630346, 2025). "Similar to MSI-H tumors, tumors with POLE/POLD1 mutations generally exhibit high tumor mutation burden (TMB)." (PMID 40308511, 2025). "By elevating tumor mutation burden and generating unique mutational signatures (e.g., SBS10d), POLD1 mutations sensitize MSS tumors to ICIs, challenging the dominance of microsatellite instability (MSI) as an immunotherapy predictor." (PMID 40661943, 2025). "Data on demographic characteristics, POLE and POLD1 alteration status, histologic subtype, tumor mutation burden, fraction of genome altered, and microsatellite instability score were collected." (PMID 38231514, 2024). "After adjusting the association values for tumor purity, we found that POLD1 was strongly linked with the majority of TILs markers in ccRCC, including several functional T cells (Th1/Th2/Th17/Tfh cells, Tregs, and exhausted T cells)." (PMID 37047824, 2023). "Nevertheless, although the germline protein expression pattern was markedly reduced in the Western Blot, the nuclear detection of POLD1 in the proband’s tumor revealed that POLD1 expression from the wild-type allele was still evident." (PMID 36756361, 2023). "To further explore the underlying function of POLD1 in tumor tumorigenesis and progression, we assessed the DEGs in the TCGA-KIRC cohort between the POLD1high and POLD1low groups." (PMID 37047824, 2023). "Our data show that DHODH overexpression with a DNA replicative polymerase (POLE and POLD1) mutation is significantly associated with high-grade (Grade III) tumor status." (PMID 38136273, 2023). "Lastly, in the patient’s tumor and cell line overexpressing POLD1 p.D402N, we found a mutational signature consistent with POLD1 exonuclease deficiency signatures." (PMID 38067377, 2023). "POLE and POLD1 encoding the catalytic subunits of DNA polymerases ε and δ play a central role in suppression of mutagenesis and tumor development by highly accurate DNA replication and exonuclease proofreading." (PMID 37990341, 2023). "A POLD1-specific mutational signature was found in both the patient’s tumor and POLD1(p.D402N) overexpressing cell." (PMID 38067377, 2023). "POLD1 expression levels in the ccRCC samples were associated with various clinical characteristics including pathologic tumor stage and histologic grade." (PMID 37047824, 2023).